GLI1 (GLI family zinc finger 1)
Diseases named in the same sentence as GLI1 in open-access papers (continued):
Sharing a sentence is not in itself a finding about the gene and the disease.
infection (13 papers, 2005 to 2023). The state of being infected such as from the introduction of a foreign agent such as serum, vaccine, antigenic substance or organism. "InSmurf1−/−;Smurf2fl/flMEFs, Ad-cre infection-mediated ablation of conditionalSmurf2fl alleles severelydampened the Gli1 transcriptional response to ShhN." (PMID 24925320, 2014). "As seen in wild-type cells, infection of Tg737Δ2–3β-gal primary limb cells with full-length Gli1 resulted in increased transcription of Ptch1 compared to infection with green fluorescent protein (GFP)–only virus." (PMID 16254602, 2005). "As seen in previous studies, infection of cells with the full-length form of Gli3 was able to repress Gli1-mediated transcription when coexpressed in wild-type cells." (PMID 16254602, 2005). "We performed analogous infections in TC‐treated Gli1‐tdTomato+ mice, and the resulting scars contained streaks of activated myofibroblasts, which stained positively for αSMA, Gli1 (via the Tomato fluorophore), and PDGFRβ, and were surrounded by areas of dense collagen deposition." (PMID 32227630, 2020). "These αSMA+, Gli1+, PDGFRβ + cells are visible in the post‐pyelonephritic scar as it forms and matures, and they become the predominant producers of TGFβ1 during resolving infection." (PMID 32227630, 2020). "Similarly, the transcription of gli1 and N-myc was elevated in the cerebellum following infection and treatment of infected mice with pred decreased the expression of both genes." (PMID 23505367, 2013). "In the case of the Gli1, Gli2, Gli3, and Gli3R proteins, localization was determined by infection of primary Tg737Δ2–3β-gal mutant and wild-type limb bud cells with adenoviral vectors that express the full-length Gli proteins or the truncated Gli3R fused to GFP." (PMID 16254602, 2005). "Seventy-two hours after infection, cells were sorted by FACS to establish new cell lines, which were named HL60/GLI1 and NB4/GLI1." (PMID 28098170, 2017). "Proliferation of MCF10a cells, which do not express endogenous GLI1, was not significantly affected by infection with the shGLI1 retrovirus." (PMID 25252859, 2014). "Although we here did not observe the significant decrease of Gli1 expression upon the infection, the nucleus/cytoplasm extraction clearly showed that the nucleus-located Gli1 significantly decreased in response to RS218 infection." (PMID 34281571, 2021).
adenocarcinoma (5 papers, 2013 to 2020). A common cancer characterized by the presence of malignant glandular cells. "The expressions of SHH and GLI1 were higher in adenocarcinoma clinical stages III and IV compared to stage II; in normal tissue, their expressions were minimal." (PMID 32867229, 2020). "Upon a specific and important reduction in the mRNA levels of Gli1 that did not affect either Gli2 or Gli3 mRNA levels, cell proliferation and cell viability was decreased in A549 adenocarcinoma cells." (PMID 23667589, 2013).
bacterial infection (3 papers, 2013 to 2020). "Overexpressing GLI1 increases G3P levels and enhances resistance against bacterial disease in Arabidopsis." (PMID 31968554, 2020). "Arabidopsis plants overexpressing GLI1/NHO1 (encoding a glycerol kinase) increase G3P levels and enhance resistance against bacterial disease caused by Pseudomonas syringae." (PMID 31968554, 2020). "To further verify the role of SHH–Gli1 signaling in the activation of primitive hematopoietic precursor cells during the granulopoietic response to serious bacterial infection, we employed an in vivo model of mice with Gli1 deletion." (PMID 29535725, 2018). "First, bacterial infection induces the production and release of Shh ligand to stimulate the recruitment of Gli1+ myeloid cells to the stomach." (PMID 23520544, 2013). "This increase in Gli1 expression in marrow lin+ cells appears to imply that the activation of the SHH signaling may also participate in the regulation of functional activities in lin-committed hematopoietic progenitors during the granulopoietic response to the systemic bacterial infection." (PMID 29535725, 2018).
central nervous system neoplasm (3 papers, 2016 to 2024). A benign or malignant, primary or metastatic neoplasm that affects the brain, meninges, or spinal cord. "Prior work showed that both Gli1 and Gli2 proteins were Class I HDAC targets in CNS tumor progenitor cells, and that de-acetylation promoted their transcriptional activities." (PMID 27668865, 2016).
prostate (2 papers, 2011 to 2022). "Identifying the regulation of stromal AR in IGFBP3 expression in Gli1-lineage FB is intriguing, suggesting an underlying mechanism for androgen-mediated IGF1 signaling activation in prostate oncogenesis." (PMID 36323713, 2022).
benign tumors (1 paper, 2009). "HH signaling in GN could be mediated by DHH, which, like GLI1 and GLI3 is differentially expressed in these benign tumors." (PMID 19834598, 2009).
cardiovascular disease (1 paper, 2023). "Glioma-associated oncogene 1 (Gli1) exerts a regulatory role on cardiovascular diseases, and it is already a therapeutic target to combat tumors." (PMID 37151880, 2023). "More functions of the Gli1 molecule in cardiovascular diseases have been explored." (PMID 37151880, 2023).
central nervous system diseases (1 paper, 2023). "These previous studies indicated that Shh/Gli-1 signaling may represent a potential therapeutic target for the regulation of microglial activation in central nervous system diseases." (PMID 36725745, 2023).
hematologic neoplasms (1 paper, 2022). "Several investigators reported reactivation of the Hh signaling pathway and its downstream effectors, such as GLI1, in hematologic neoplasms including MPN." (PMID 35595725, 2022).
GLI1 also shares sentences with these, for which no sentence is quoted: idiopathic pulmonary fibrosis (5 papers); alveolar rhabdomyosarcoma (3); hematological malignancies (3); lung disease (3); myelodysplastic syndrome (3); pancreatitis (3); soft tissue sarcoma (3); acute lymphoblastic leukemia (2); autism (2); benign prostatic hyperplasia (2); congenital heart disease (2); cyclopia (2); gastrointestinal stromal tumor (2); ischemic stroke (2); myocardial infarction (2); myoepithelial tumor (2); nevus (2); non-melanoma skin carcinoma (2); acute leukemia (1); acute megakaryoblastic leukemia (1); adenoid cystic carcinoma (1); adenomatoid odontogenic tumor (1); adenosis (1); alcoholic liver diseases (1); alveolar soft part sarcoma (1); Barrett ́s esophagus (1); basal cell adenocarcinoma (1); benign mesothelioma (1); biliary atresia (1); calcific aortic valve disease (1).
A further 80 diseases each share a sentence with GLI1 in 1 paper.